AR (androgen receptor)
Diseases named in the same sentence as AR in open-access papers (continued):
Sharing a sentence is not in itself a finding about the gene and the disease.
breast carcinoma (continued). "Its correlation to biological features associated with breast cancer have not been fully established, especially in the context of the association of androgens or AR signaling." (PMID 31664946, 2019). "Approximately 77% patients with breast cancer were estimated to be AR positive." (PMID 31126320, 2019). "The treatment effect for BCFI was suggestively stronger among AR− breast cancers (HR[Let.:Tam.] = 0.39, 95% CI 0.21–0.72, p = 0.002) than among AR+ breast cancers (HR[Let.:Tam.] = 0.63, 95% CI 0.47–0.85, p = 0.003), though this difference was not statistically significant (p-heterogeneity = 0.16)." (PMID 30795773, 2019). "To confirm that steroidal AIs and their 17-OH derivatives reduce the growth of ER(+) breast cancer cells by activating AR, we investigate whether these compounds can bind to AR protein and promote AR transcriptional activity." (PMID 31235695, 2019). "We investigated if sPSA reflects tumor biology, including AR signaling in breast cancer patients." (PMID 31664946, 2019). "AR blockade can resensitize cells, and therefore is potential target in ER+ breast cancer." (PMID 31238876, 2019). "An AR:ER ratio ≥ 2 was associated with an increased rate of tamoxifen failure in a cohort of 192 women with ER+ breast cancer, though these tumors may be more receptive to treatment with AR-antagonists." (PMID 30795773, 2019). "If sPSA levels reflect the amount of AR signaling or AR dependency of the tumor in breast cancer patient, it may be useful for effective treatment selection." (PMID 31664946, 2019). "We explored the effect of AR depletion in breast cancer cells." (PMID 31126320, 2019). "AR expression in the primary breast cancers correlated with expression of p-HER2, EGFR, p-EGFR, p-IGFR, and p-ERK in patients who did not benefit from letrozole plus dasatinib (PFS ≤ 6 months), suggesting a potential interaction between AR and HER family receptors in letrozole/dasatinib resistance." (PMID 31667338, 2019). "MCF-7 and ZR-75-1 cells are breast cancer cells expressing ERα and AR." (PMID 31235695, 2019). "Based on the result of present study, we hypothesize that PSA may be useful for effective treatment selection, especially for AR-targeting therapies in post-menopausal breast cancer patients." (PMID 31664946, 2019). "Clinically, strategies that aim to block AR and ER, namely, androgen deprivation therapy and selective ER modulators, are widely employed to treat prostate and breast cancer, respectively, strongly supporting the practicality of NRs as druggable targets to improve cancer treatment outcomes." (PMID 30925918, 2019). "This negative association between AR and histological grade has been reported in multiple publications on breast cancers, including in TNBCs alone." (PMID 31888566, 2019). "Similarly, in the medical literature, most publications report a very strong correlation between FOXA1 positivity in breast cancers and the expression of the hormone receptors ER and PR, confirmed by two meta-analyses, AR, and the luminal-A phenotype." (PMID 31888566, 2019). "We previously reported that CCND1 represents a target gene of DHT-activated AR in MCF-7 breast cancer cells, evidencing the existence of a functional Androgen Response Element within the CCND1 promoter, which mediates the DHT/AR inhibitory effects on basal breast cancer cell proliferation." (PMID 31684907, 2019). "AR is expressed in 50–90% of breast cancers and some claim that it is more common than ER or PR." (PMID 31151151, 2019). "Indeed, several events involved in breast cancer genesis or progression have been shown to alter AR expression or function." (PMID 31684907, 2019). "Given the purported antagonistic effects of AR signaling in ER+ breast cancer, we postulate that the efficacy of letrozole may be stronger in AR+/ER+ cancers." (PMID 30795773, 2019).
breast carcinoma (continued). "Interestingly, NF1 mutations are high in a TNBC subtype called “apocrine TNBC” with relatively high expression of androgen receptor (AR), although TNBC is overall lower in AR expression than other breast cancer subtypes." (PMID 30630526, 2019). "We hypothesize that there are some correlations among AR, let-7a and BT-IC, and they maybe co-regulate the progression of breast cancer." (PMID 29423076, 2018). "There was little evidence for an overall association between AR expression in normal breast tissue and breast cancer risk." (PMID 30276234, 2018). "AR activation could decrease the mammospheres formation, while AR knockdown increase in ER+AR+ breast cancer cells when they were cultured in suspension." (PMID 29423076, 2018). "In contrast, AR‐ breast cancer lines MDA‐MB‐231 and MDA‐MB‐468 have low expression levels of SRARP." (PMID 29577611, 2018). "As AR has a dichotomous role in breast cancer, AR agonists, or antagonists may offer therapeutic benefit perhaps dictated, in part, by subtype specificity." (PMID 30416486, 2018). "The AR-positive breast cancer MDA-MB-453 cells have a similar molecular profiling to LAR subtype." (PMID 29713287, 2018). "AR-negative status was associated with a shorter time to progression, with AR negative AA women demonstrating a shorter time to breast cancer progression and the worst overall survival." (PMID 29912871, 2018). "The next several articles review the possible role of androgens and AR signaling in breast cancer, bladder cancer, salivary gland cancer, and hepatocellular carcinoma, as well as the potential treatment implications of using antiandrogen therapies in these non-prostatic malignancies." (PMID 29346310, 2018). "AR is expressed in about 70–90% of breast cancers and seems to play a major role in carcinogenesis." (PMID 30547831, 2018). "We found more tumor cells with CD44+/CD24-/low phenotype could be detected in ER-positive and AR-positive breast cancers." (PMID 29423076, 2018). "In a tumour environment depleted of estrogen or where estrogenic action is inhibited, AR-overexpressing breast cancer cells may acquire alternative proliferation mechanisms through AR-dependent intracellular ER-signalling." (PMID 29895278, 2018). "Sex steroid hormone signaling is critical in the development of breast cancers, although the role of the androgen receptor remains unclear." (PMID 30276234, 2018). "The question whether inflammatory cytokines such as IL-6 cooperate with stromal-derived estrogen and sensitize breast cancer cells to ER, as we observe for testosterone signaling through the androgen receptor, remains to be determined." (PMID 29898754, 2018). "Therefore, ER+AR+ breast cancer cell lines, MCF7 and T47D were selected to perform the following analysis." (PMID 29423076, 2018). "Together, our CRISPR rat Nf1 model and our WGCNA analysis of human breast cancer confirms that NF1 is intricately connected to ER networks, including several genes that have been directly linked to endocrine resistance (i.e., FOXA1 and AR)." (PMID 30182054, 2018). "The androgen receptor (AR) is expressed in 50–70% of all breast cancer." (PMID 29991699, 2018). "However, the role of AR in breast cancer development and progression is mired in controversy with evidence suggesting it can either inhibit or promote breast tumorigenesis." (PMID 30416486, 2018). "Notably, SRARP is highly co‐expressed with AR in breast cancer cell lines, primary breast tumors, and metastatic breast cancer." (PMID 29577611, 2018). "This is an active area of research and understanding and modulating the activity of membrane AR may be a key component in determining full clinical response to anti-AR therapies in subsets of breast cancer patients." (PMID 30416486, 2018). "Our data suggested that AR/let-7a signaling could inhibit the biological behavior of tumor-initiating cells (T-IC) in ER+AR+ breast cancers, which might become a new therapeutic target." (PMID 29423076, 2018).
breast carcinoma (continued). "Ki67 did not modify the association between AR expression and breast cancer risk (p interaction = 0.75)." (PMID 30276234, 2018). "Although a discordance between the levels of RNA transcripts and protein expression does exist, further analyses are required to determine whether current immunohistochemical approaches can accurately predict AR-positivity in breast cancer." (PMID 30279965, 2018). "AR dominant signaling prevents breast cancer recurrence and metastasis, especially in MBC patients." (PMID 30577860, 2018). "Kevin Kensler from the Dana-Farber Cancer Institute in Boston, Massachusetts, USA, and colleagues quantified expression of the androgen receptor (AR) in biopsy tissue taken from 354 women with benign breast disease, 78 of whom were later diagnosed with breast cancer." (PMID 30276234, 2018). "However, little information is known about the correlations between AR and breast T-IC capabilities in breast cancers." (PMID 29423076, 2018). "Furthermore, in a recent study looking at the role of AR in breast cancer and its expression in circulating tumor cells (CTC) and bone metastasis, the authors report that AR is both transcribed and active in breast cancer to bone metastasis." (PMID 30416486, 2018). "Therefore, we set out to identify the extent of AR expression within all three breast cancer subtypes." (PMID 30279965, 2018). "The Castanas group has led the field in understanding the role of membrane AR in breast cancer." (PMID 30416486, 2018). "The androgen receptor is an emerging biomarker of interest in breast cancer." (PMID 30276234, 2018). "Compared to women with low AR/low ER expression, women with high AR/high ER expression had a non-significant 60% lower risk of breast cancer (OR = 0.4, 95% CI = 0.1–1.2)." (PMID 30276234, 2018). "Numerous studies have reported that approximately 80% of breast cancers are positive for AR, furthermore AR protein is detectable across luminal A (ERα+ve, PR+ve, Her2-ve), Luminal B (ERα+ve, PR+ve, Her2+ve), triple-negative/basal (ER-ve, PR-ve and Her2-ve) and Her2 amplified (Her2+)." (PMID 30416486, 2018). "And more studies should be carried out to analyze whether let-7a will down-regulate AR expression and affect androgen-AR signaling in breast cancer cells." (PMID 29423076, 2018). "From the present and our previous study, we concluded that the inhibition of some biological behavior of breast cancer cells induced by AR signaling might be via let-7a up-regulation in part." (PMID 29423076, 2018). "We speculated that the mechanism of AR affecting breast T-IC might be partially via transcriptional regulation of let-7a, since let-7a overexpression inhibits T-IC capabilities in ER+ breast cancers." (PMID 29423076, 2018). "In addition to this, a study exploring the role of phosphorylated AR in breast cancer progression noted that particularly in ERα –ve and invasive ductal carcinoma types, there was higher levels of phosphorylated AR in the cytoplasm than the nucleus." (PMID 30416486, 2018). "Our previous results indicate AR activation may increase let-7a expression in breast cancer cells, while let-7, a tumor suppressor, is reported to inhibit breast tumor-initiating cells (T-IC)." (PMID 29423076, 2018). "We reported that these tumors were of a molecular apocrine histology and have since gained an interest in understanding how AR could be used as a possible biomarker of a specific subtype of breast cancer." (PMID 30279965, 2018). "In both male and female breast cancers, the majority of AR sites are also occupied by ERα." (PMID 30416486, 2018). "Most studies examining the expression of AR in breast cancer have concentrated on the TNBC subtype." (PMID 29912871, 2018). "However, clinical studies in breast cancer to date have shown mixed response to blockade of AR signalling." (PMID 29991699, 2018).
breast carcinoma (continued). "Preclinical studies have surmised that AR may enact its protective role by blocking ERα gene transcription, however, other studies in triple-negative and apocrine breast cancers indicate that AR may act as a pseudo- ERα in this setting." (PMID 30416486, 2018). "It is reported that AR/ER ratio can influence cells response to androgen, and increased ratio of AR/ER inhibits E2-induced proliferation, which further illustrate that AR may function in breast cancer dependent on ER expression." (PMID 29423076, 2018). "Androgen receptor (AR) has been shown to have prognostic implication on breast cancer (BC)." (PMID 29651273, 2018). "Targeting of AR may have a large impact as a novel therapeutic strategy for treating Herceptin resistant HER2-positive breast cancers or could even be considered as a strong candidate for combination therapy." (PMID 30279965, 2018). "We also observed that the absence of AR expression is more prevalent in AA women in all breast cancer subtypes, however AR loss is most frequently observed in TNBC patients, which is referred to as “QNBC”." (PMID 29912871, 2018). "ERK1/2 is known to phosphorylate AR on serine-515 in breast cancer." (PMID 30416486, 2018). "Trials have reported varied response rates dependent upon subtype with overall clinical benefit rates of ~19–29% for anti-androgen monotherapy, suggesting that with enhanced patient stratification AR could prove efficacious as a breast cancer therapy." (PMID 30416486, 2018). "Also in luminal A (ER+ve, AR+ve) breast cancer MCF7 cells, the cyclin D1 promoter has been identified as harboring a functional ARE." (PMID 30416486, 2018). "The expression of the androgen receptor (AR) was also found to be prognostic; this agrees with previously published data that shows improved long-term survival with co-expression of AR in ER positive breast cancers." (PMID 29707132, 2018). "There is a dynamic, context dependent relationship between AR and ER DNA binding in breast cancer." (PMID 30416486, 2018). "Immunohistochemical studies of breast cancers have shown that whilst the majority of tumors express some degree of AR protein (>1%) there is also a huge diversity in the percentage of cells within a tumor expressing the protein and also the relative abundance of the protein present." (PMID 30416486, 2018). "Furthermore, dual regulatory effects of AR on SRARP expression are consistent with the fact that these genes are highly co‐expressed in breast cancer." (PMID 29577611, 2018). "While there were few individuals with low AR and high ER, they experience apparent higher risk of breast cancer, though again this was not statistically significant." (PMID 30276234, 2018). "Selective Androgen Receptor Modulators (SARMs) such as enobosarm are being explored for clinical use as they may counteract the activity of ER in driving breast cancer growth." (PMID 30416486, 2018). "Among the 47 cases and 127 controls with measured AR and ER expression, there was no significant heterogeneity of the association between AR expression and the incidence of breast cancer by co-expression of ER in normal tissue (p heterogeneity = 0.21)." (PMID 30276234, 2018). "In addition to its well characterized role in sexual development, AR has gained increasing attention as an important mediator of hormone-dependent cancers and a novel therapeutic target in breast cancer." (PMID 30279965, 2018). "Therefore, SIRT1 seems to exert tumor-suppressive properties in apocrine breast cancer as well, through epigenetic repression of the AR oncogene." (PMID 30093977, 2018). "We inferred that androgen/AR signaling might transcriptionally mediate the regulation of let-7a in ER+AR+ breast cancer cells, just like the mechanism in ER-AR+ breast cancer cells." (PMID 29423076, 2018).
breast carcinoma (continued). "In this study, we examined expression of AR and VDR, phosphorylation of AKT Ser473 (AKT phospho-Ser473) and ERα Ser167 (ERα phospho-Ser167), and the mutational status of the PIK3CA gene in ER-positive, HER2-negative early breast cancer tissues." (PMID 29707142, 2018). "It has been shown in prostate and breast cancers that AR activation might be achieved through ligand-independent mechanisms." (PMID 29731997, 2018). "Interestingly, C1orf64 shows a strong correlation with SPDEF expression in breast cancer at a level similar to that observed with AR." (PMID 28915724, 2017). "If AR+ER− breast cancer is confirmed to have inferior prognosis, this may impact the choice of AR-targeted treatments and reveal a need for closer surveillance of this patient group." (PMID 28643022, 2017). "Importantly, AR activation in breast cancer cells induces endogenous factor VII (FVII) activity to convert factor X to Xa in conjunction with the tissue factor (TF)." (PMID 28915724, 2017). "Given the size of these studies, and the unique look into male breast cancer, they remain important and will be discussed briefly here prior to reviewing the significance of AR in relation to ER in this section, and HER2 co-expression versus TNBC in later sections." (PMID 28245550, 2017). "Not much is known about the control of the expression of HSD17B1 and HSD17B2 in breast cancer, apart from that they are correlated with ERα expression, and that dihydrotestosterone can induce HSD17B2 expression in an AR-dependent manner in the breast cancer cell line T-47D." (PMID 28977936, 2017). "This study assessed the role of AR phosphorylation at ser81/ser515 and their two upstream effectors, cyclin-dependent kinase 1 (pCDK1) and extracellular-regulated kinase 1/2 (pERK1/2) in 332 ductal breast cancer patients by immunohistochemistry." (PMID 28415597, 2017). "In this prospective cohort with long-term follow-up, breast cancer patients with AR+ tumors had lower BCM but not all-cause mortality compared to patients with AR− tumors." (PMID 28643022, 2017). "Other clinical studies also showed AR expression is higher (n = 573, 85%) among all breast cancer, however, multivariable analysis for short-term follow-up indicated higher metastasis among patients with AR+ER- tumors (HR 3.5; 95% CI 1.4-9.1) than other (AR and ER combinations)." (PMID 29254284, 2017). "Importantly, multiple preclinical studies have suggested a potential role for AR as a therapeutic target in breast cancer and currently this topic is under active investigation in clinical trials." (PMID 28915724, 2017). "This phenomenon has been detected in other hormone-dependent tumours, such as breast cancer, and has important implications for treatment strategies, as CTCs AR status could be a potential marker of response to AR-targeting therapies." (PMID 29050295, 2017). "The mechanisms linking height to post-menopausal breast cancer risk may go through Ihh signalling as well as ERBB4 signalling and androgen receptor signalling." (PMID 28117334, 2017). "In addition, there was a strong correlation between AR RNA and protein expression levels, and this correlation remained significant across all subtypes of breast cancer." (PMID 28840192, 2017). "Overexpression of AR in the MCF-7 breast cancer cell line, as postulated by Britton and colleagues, is thought to be due to cross talk between ERα and the EGFR/MAPK pathway, which leads to a self-propogating autocrine growth-regulatory loop through ERα mediated development of AR." (PMID 28245550, 2017). "The data also suggests that AR may be an important regulator of inflammation in breast cancer and maybe a potential prognostic biomarker for TNBC." (PMID 28415597, 2017). "Hence, a detailed understanding of the potential role of AR in breast cancer is essential to design and develop a newer class of treatment option for the patients." (PMID 29254284, 2017). "The current interest in AR in breast cancer is multilayered." (PMID 28643022, 2017).